S100A4 (S100 calcium binding protein A4)
Description:
Calcium-binding protein that plays a role in various cellular processes including motility, angiogenesis, cell differentiation, apoptosis, and autophagy. Increases cell motility and invasiveness by interacting with non-muscle myosin heavy chain (NMMHC) IIA/MYH9. Mechanistically, promotes filament depolymerization and increases the amount of soluble myosin-IIA, resulting in the formation of stable protrusions facilitating chemotaxis (By similarity). Within the extracellular space, stimulates cytokine production including granulocyte colony-stimulating factor and CCL24 from T-lymphocytes (By similarity). In addition, stimulates T-lymphocyte chemotaxis by acting as a chemoattractant complex with PGLYRP1 that promotes lymphocyte migration via CCR5 and CXCR3 receptors.
Synonyms: CAPL; MTS1; P9KA; 18A2; PEL98; 42A; FSP1
Tractability: Small molecule: a structure with a bound ligand is known; a high-quality ligand is known. Antibody: UniProt places it where antibodies can reach, with high confidence; its Gene Ontology location is reachable by antibodies, with medium confidence. PROTAC: ubiquitination databases record sites on it; its protein half-life has been measured; a small molecule that binds it is known.
Gene: Protein-coding gene on chromosome 1 (153,543,613 to 153,550,136, reverse strand). Ensembl gene ENSG00000196154.
Subcellular location: Secreted; Nucleus; Cytoplasm
Subcellular location (Human Protein Atlas): Nucleoplasm; Cytosol; Predicted to be secreted
Gene Ontology:
Molecular function: chemoattractant activity; identical protein binding; protein binding; RAGE receptor binding; RNA binding; calcium ion binding; calcium-dependent protein binding; actin binding; transition metal ion binding
Biological process: positive regulation of canonical NF-kappaB signal transduction; epithelial to mesenchymal transition; positive chemotaxis
Cellular component: extracellular exosome; extracellular matrix; extracellular region; nucleoplasm; nucleus; perinuclear region of cytoplasm; cytoplasm
Genetic constraint (gnomAD): Loss-of-function variants: 4 observed, 8.09 expected, observed/expected ratio (o/e) 0.49, 90% interval 0.24 to 1.13. That is too few expected variants to judge how well the gene tolerates losing a copy. Missense variants: 108 observed, 127.44 expected, observed/expected ratio (o/e) 0.85, 90% interval 0.72 to 0.99. Synonymous variants: 44 observed, 49.91 expected, observed/expected ratio (o/e) 0.88, 90% interval 0.69 to 1.13.
Homologues: Orthologues: chimpanzee S100A4 (100% identical), macaque S100A4 (100% identical), pig S100A4 (99% identical), rabbit S100A4 (98% identical), dog S100A4 (95% identical), guinea pig S100A4 (95% identical), mouse S100a4 (93% identical), rat S100a4 (91% identical), zebrafish s100t (47% identical), zebrafish s100s (46% identical), zebrafish s100a10a (32% identical), tropical clawed frog s100a11 (25% identical). Paralogues in human: S100A2 (58% identical), S100A5 (47% identical), S100A6 (47% identical), S100A1 (46% identical), S100Z (44% identical), S100A3 (43% identical), S100B (41% identical), S100P (39% identical), S100A10 (35% identical), S100A16 (33% identical), S100A13 (32% identical), S100A12 (30% identical), and 9 more.
Diseases named in the same sentence as S100A4 in open-access papers:
S100A4 is named in the same sentence as 304 diseases in open-access papers, as found by Europe PMC text mining. Sharing a sentence is not in itself a finding about the gene and the disease. The quoted sentences say what the papers report.
breast carcinoma (146 papers, 2002 to 2025). "S100A4 monoclonal antibodies significantly limit breast tumor invasion and metastasis in vivo and bone loss caused by breast cancer bone metastasis." (PMID 39830522, 2024). "Further, the inflammatory cytokine pentraxin 3 (PTX3) has been observed to change in poorly‐differentiated clinical breast cancer samples and the S100 calcium binding family member S100A4 has been implicated in endometrial cancer progression through EMT." (PMID 37217832, 2023). "In breast cancer, the S100A4/PDPN expression ratio in CAFs is associated with disease outcomes across subtypes." (PMID 37894446, 2023). "CAFs with concurrent expression of α-SMA and S100A4 in breast cancers were associated with lymph node metastases." (PMID 36768815, 2023). "The next pathway, ESR1, which was mutated in breast cancer, received microenvironment factor S100A4 to regulate TF ETS1 and SMAD3 through signaling transduction proteins ZNF516, PIK3R1, IDH1, and AKT1." (PMID 33802957, 2021). "In fact, elevated levels of the calcium-binding protein S100A4 have been associated with poor patient survival in breast cancer patients and to induce metastasis in rodent models." (PMID 33114046, 2020). "High levels of S100A4 protein in human carcinoma cells are strongly associated with their metastatic capability S100A4 was demonstrated to be a strong indicator of a poor prognosis of human breast cancers." (PMID 32012176, 2020). "Both CYR61 and S100A4 alter breast cancer invasiveness but the underlying molecular mechanisms remain elusive." (PMID 31709177, 2019). "Taken together, our results suggest that S100A4 released from breast cancer cells is an important player in the osteolysis caused by breast cancer bone metastasis." (PMID 31667000, 2019). "In conclusion, targeting the S100A4–RAGE interaction is a valid approach for inhibiting the bone destruction caused by breast cancer metastasis." (PMID 31667000, 2019). "In this study, we investigated the effect of the metastasis‐ and inflammation‐associated microenvironmental factor S100A4 on breast cancer cells (BCCs) of different subtypes and explored their further interactions with myeloid cells." (PMID 29741811, 2018). "A fraction of researchers have reported that S100A4 overexpression significantly correlates with histological grade and loss of estrogen receptors in breast cancer." (PMID 29069865, 2017). "Integrin α6β4 signaling led to the demethylation of the S100A4 promoter associated with breast cancer progression." (PMID 29069865, 2017). "Although staining for three MIPs is somewhat elevated in these BMs, only that for S100A4 shows a significant association with clinical outcomes in the form of time to intracranial progression in all BMs, and OS in breast cancer and melanoma BMs." (PMID 27100728, 2016). "Two genes that have been linked to breast cancer progression, IL-8 and S100A4, were differentially modulated by every cell culture modification that we examined." (PMID 25776572, 2015). "S100A4 has been associated with migratory and invasive properties and is able to induce metastasis in rodent models of breast cancer." (PMID 21629247, 2011). "When highly metastatic mouse mammary carcinoma cell line expressing high levels of S100A4 protein was introduced into S100A4-deficient mice, a severe impairment both in tumour incidence and uptake was observed." (PMID 15900299, 2005). "Studies on 62 breast carcinomas of I–IV stages revealed significant correlation of S100A4 immunoreactivily with histological grade and loss of oestrogen receptor but not with the development of distant metastasis and patient survival." (PMID 15900299, 2005). "Elevated levels of the calcium-binding protein S100A4 are associated with poor patient survival in breast cancer patients and induce metastasis in rodent models." (PMID 14710237, 2004).
breast carcinoma (continued). "We examined by immunohistochemistry the protein expression of S100A4, a metastasis-associated protein, in human breast cancer specimens." (PMID 12439718, 2002). "The presence of the EF-hand-calcium-binding protein S100A4 in the carcinoma cells of the primary tumour is associated with a shorter survival time of a group of breast cancer patients." (PMID 11875708, 2002). "S100A4 has been shown to cause metastasis in rodent models of breast cancer, and its presence in breast cancer cells is strongly associated with death of a group of patients with human breast cancer." (PMID 11875708, 2002). "In a study of 349 patients with breast cancer, the presence of immunocytochemically-detectable S100A4 in the primary tumours is associated with their early demise when followed up for 19 years." (PMID 11875708, 2002). "The EF-hand-containing protein, S100A4 (p9Ka) is closely linked with the ability of mammary tumour cells to metastasize in experimental model systems." (PMID 11875708, 2002). "For instance, while comparing molecular profiles of the gene group associated with the metastasis of breast cancer cells in bones, it was demonstrated that the cells selected for their predominant metastasis in the bone tissue had the decreased S100A4 expression levels." (PMID 35546077, 2022). "Previously we have demonstrated that both S100A4 and S100P are able to promote metastasis in syngeneic rat models for breast cancer and that their overexpression in human primary breast cancers is associated with poor patient prognosis due to metastasis, at least to the brain and the liver." (PMID 32065231, 2020). "Therefore, we propose that S100A4 is a major contributor to osteoclast development and bone destruction associated with breast cancer bone metastasis." (PMID 31667000, 2019). "Overall, targeting S100A4 alone or in combination with driver mutations such as PIK3CA may provide a durable therapeutic intervention opportunity in aggressive breast cancers." (PMID 31881983, 2019). "S100A4 has been previously associated with poor prognosis in breast cancer patients." (PMID 29069865, 2017). "Thus, S100A4 could be used as a predictive marker because S100A4 overexpression has been strongly associated with poor prognosis of breast cancer and colorectal cancer (CRC)." (PMID 29069865, 2017). "Multiple S100A4 blocking antibodies have been reported and evaluated in preclinical models of breast cancer, prostate cancer, HCC, CRC, and skin fibrosis." (PMID 40078995, 2025). "In previous studies, TGFβI and S100A4 have also been found to be highly expressed in diseases such as osteoarthritis and breast cancer." (PMID 40821652, 2025). "Using the MMTV-PyMT spontaneous metastatic breast cancer mouse model, one study showed that S100A4 secretion by fibroblasts promotes T cell accumulation in pulmonary metastatic sites to promote metastasis to the lung." (PMID 40078995, 2025). "In mouse models of breast cancer metastasis to the lung, macrophage-derived S100A4 promotes formation of the premetastatic niche via activation of lung fibroblasts." (PMID 40078995, 2025). "S100A4 is also known as fibroblast specific protein-1 (FSP-1), among other names, as a gene highly expressed in breast cancer associated fibroblasts." (PMID 40078995, 2025). "They demonstrated that extracellular S100A4 promotes secretion of pro-inflammatory cytokines by breast cancer cells, which triggers THP-1 monocyte-to-macrophage differentiation." (PMID 40078995, 2025). "THP-1 TAMs conditioned in S100A4+ breast cancer cell culture media in turn promote mesenchymal transition of breast cancer cells." (PMID 40078995, 2025). "In this context, chromatin-bound S100A4 is expelled from apoptotic metastatic breast cancer cells, which then activates RAGE receptors in neighboring surviving tumor cells." (PMID 39830522, 2024).
breast carcinoma (continued). "Over-expression of S100A4 has been reported in multiple cancers, such as gastric, colorectal and breast cancers." (PMID 39205741, 2024). "For example, it has been reported that S100A4 is upregulated in breast cancer and is involved in promoting cancer metastasis." (PMID 38842658, 2024). "It has also been shown that in breast cancer, ECM1 can regulate the actin cytoskeleton structure of invasive breast cancer cells through the regulation of S100A4 and Rhoa." (PMID 39418248, 2024). "S100A4 overexpression in breast cancer cells provides increased migratory capacity as the interaction with MMP2 induces EMT." (PMID 39830522, 2024). "S100A4 is associated with poor survival in THCA as well as in glioma, bladder, pancreatic, and breast cancers." (PMID 39335579, 2024). "S100A4 has been previously recognized to play a crucial role in promoting lung metastasis of breast cancer." (PMID 37400459, 2023). "The fact that RGC’s IC50 for the degradation of S100A4 in and the migration of the human breast cancer cell line MDA-MB-231 are similar at 3.2 and 3.5 nM, respectively suggests that RGC is operating through a common mechanism." (PMID 37509135, 2023). "S100A4 released from highly bone-metastatic breast cancer cells plays a critical role in osteolysis." (PMID 36817136, 2023). "These indicated that S100A4 mediates the functions of STC1 in breast cancer cells and tumor microenvironments." (PMID 37400459, 2023). "STC1 upregulates the expression of S100A4 in breast cancer cells by promoting EGFR phosphorylation and ERK signaling." (PMID 37400459, 2023). "In breast carcinoma mouse models, in vivo experiments demonstrated the role of S100A4 expressed by stromal fibroblasts to stimulate metastasis formation." (PMID 36768815, 2023). "By overexpression and knockdown of S100A4, we demonstrated that S100A4 can promote breast cancer cell invasion, enhance vascular endothelial cell tube formation, and promote fibroblast activation." (PMID 37400459, 2023). "S100A4 mainly exists in the tumor microenvironment and acts as an extracellular factor on breast cancer cells (BCC) to recruit immune cells to the tumor." (PMID 36560848, 2023). "S100A4 participates in the recruitment of T lymphocytes and the release of cytokines, thereby stimulating the metastasis of breast cancer." (PMID 36560848, 2023). "We noticed that the knockdown of S100A4 restored the promotional action of STC1-overexpressing breast cancer cells on these functions, and overexpression of S100A4 rescued the inhibitory effect of STC1 knockdown breast cancer cells on these functions." (PMID 37400459, 2023). "Knockdown of S100A4 expression in the breast cancer cell line MDA-MB-231 inhibited cell migration and invasion and significantly inhibited EMT." (PMID 37033662, 2023). "Another study showed that extracellular ATP promotes interactions between breast cancer cells and fibroblasts, where S100A4 is produced in collaboration with breast cancer cells to exacerbate breast cancer metastasis." (PMID 37496657, 2023). "Our findings showed that S100A4 can mediate the effect of breast cancer cells with high STC1 expression on lung fibroblasts." (PMID 37400459, 2023). "Relying on transcriptome sequencing screening, we found that the target of STC1 in breast cancer cells is S100A4." (PMID 37400459, 2023). "More detailed investigations established that S100a4 was the most inhibited gene in osteotropic breast cancer cells." (PMID 35546077, 2022). "Overexpression of S100A4 was observed in several types of metastatic cancer, including epithelial ovarian carcinoma, prostate cancer, breast cancer, and pancreatic cancer." (PMID 35214097, 2022). "S100A4′s metastasis inducing potential is not only important in breast cancer but in many other solid tumor entities such as lung, colon, gastric, esophageal, hepatocellular, pancreatic, gallbladder, ovarian and prostate cancer." (PMID 35326507, 2022).
breast carcinoma (continued). "The calcium-binding protein S100A4 was first described as a metastasis-inducing protein in breast cancer in 1993." (PMID 35326507, 2022). "In order to utilize the natural targeting characteristic, the membrane of sEVs derived from breast cancer cells was extracted and wrapped around cationic bovine serum albumin-conjugated S100A4 siRNA." (PMID 36212432, 2022). "S100A4 is identified as significantly expressed in the biopsies of breast cancer hyperplasia and in malignant breast tumors." (PMID 35546077, 2022). "These biomimetic nanoparticles displayed gene-silencing effects on S100A4, which was an important metastasis-related protein that promotes tumor progression and metastasis and suppressed postoperative breast cancer metastasis." (PMID 36212432, 2022). "In this regard, we discovered that macrophages aid breast cancer metastasis by secreting S100A4, which makes healthy lung fibroblasts become α-SMA+ myofibroblasts that release high levels of ECM proteins." (PMID 35496059, 2022). "A breast cancer model study revealed that metastatic tumors exhibited high S100A4 expression and contained a high percentage of epithelial-mesenchymal transition signature-positive cells." (PMID 35214097, 2022). "CD36 in TAMs mediates FA uptake through S100A4-PPAR-γ axis that promotes tumor growth in a mouse models of breast cancer and fibrosarcoma." (PMID 36686729, 2022). "In the model of spontaneous breast cancer, blocking the antibody of S100A4 can affect tumor growth and metastasis." (PMID 33912559, 2021). "Overexpression of S100A4 in MDA-MB-231 breast cancer cell line up-regulated MMP13 expression resulted in an increased cancer cell migration and angiogenesis." (PMID 34209679, 2021). "Anti-S100A4 mAb treatment significantly reduced metastatic burden in the lungs of a mammary carcinoma model by blocking the recruitment of T cells to the site of the primary tumor." (PMID 34209679, 2021). "In summary, to the best of our knowledge, our study is the first to confirm that a Chk1 inhibitor combined with γ-irradiation suppresses the invasiveness of breast cancer cell lines, resulting from inhibiting the expression of S100A4." (PMID 34124754, 2021). "Recently, we have reported that S100A4 promotes osteolytic bone metastasis in breast cancer by regulating cell migration and osteoclastogenesis." (PMID 33549040, 2021). "Our previous study on bone-metastatic breast cancer showed that RAGE plays a crucial role in S100A4-stimulated osteoclastogenesis." (PMID 33549040, 2021). "Corroborating these findings, an increased level of S100A4 has been detected in breast cancer interstitial fluid and in the serum of S100A4 transgenic mice." (PMID 33946884, 2021). "In breast cancer, the positive correlation between S100A4 expression and cancer progression has been described in several studies." (PMID 32344524, 2020). "In this context, an anti-S100A4 antibody, named 6B12, showed immunomodulatory activity by binding S100A4 and thereby preventing T-cell attraction to the tumour side, which reduced metastasis in lung and breast cancer within experimental mouse models." (PMID 32722137, 2020). "CTGF enhances cell motility in breast cancer through integrinαVβ3-ERK1/2 dependent S100A4 upregulation." (PMID 33087801, 2020). "S100A4 is highly involved in metastasis and invasion of many different cancer types, including breast cancer." (PMID 32722137, 2020). "Since increased level of S100A4 was observed in a tumour interstitial fluid of breast cancer, immune cells, at least of myeloid origin, are thought to be the source of extracellular S100A4 in the damaged tissues." (PMID 32307910, 2020). "Podoplanin+S100A4+PDGF-Rα+ fibroblasts are present in bone metastasis sites of human breast cancer patients." (PMID 33050237, 2020). "Blocking extracellular signaling of S100A4 reduced invasiveness of breast cancer cells in a 2D transwell invasion assay." (PMID 31709177, 2019).